IGFBP2 (insulin like growth factor binding protein 2)
Diseases named in the same sentence as IGFBP2 in open-access papers (continued):
Sharing a sentence is not in itself a finding about the gene and the disease.
cancer (continued). "Combined biomarker panels (IGFBP2, LCAT and CA125) outperformed CA125 up to 3 years pre-diagnosis, identifying cancers missed by CA125, providing increased diagnostic lead times for Type I and Type II OC." (PMID 28664912, 2017). "The interaction of the Arg-Gly-Asp motif in IGFBP2 with integrins typically results in stimulatory effects towards cancer cells." (PMID 27579675, 2016). "Evaluation of IGFBP2 as a biomarker in the treatment of cancer has also generated a dichotomy in how IGFBP2 is perceived." (PMID 25774149, 2015). "In general, IGFBP2 is considered to be oncogenic and its expression is often observed to be elevated in cancer." (PMID 25774149, 2015). "So far, it is clear that IGFBP2 has profound effects on cancer cell biology both in vitro and in vivo and therefore warrants further evaluation of IGFBP2 either as a biomarker or even as a therapeutic." (PMID 25774149, 2015). "There are a number of additional factors, which are known to influence IGFBP2 expression, and therefore how we evaluate its role in cancer." (PMID 25774149, 2015). "This transient exposure of cancer cells to adipocyte-derived IGFBP-2 then durably increases metastasis even when the two cell types are no longer interacting." (PMID 25747684, 2015). "In this mini-review, we discuss the factors influencing the variation in IGFBP2 expression in cancer and our interpretation of these findings." (PMID 25774149, 2015). "It is, therefore, conceivable that the IGFBP-2 induced increase in cancer cell invasiveness can be counteracted to some extent." (PMID 25747684, 2015). "In this cohort, patients with higher IGFBP2 expression had worse overall survival, even when controlled for cancer stage (p = 0.033, log rank test)." (PMID 26317790, 2015). "The authors discussed the potential use of Sp1 inhibitors particularly in cancers that highly express IGFBP-2." (PMID 24778626, 2014). "We further measured IGFBP2 expression in a number of human cancer cell lines including AML and ALL lines." (PMID 24191913, 2013). "Further investigations are warranted to determine how IGFBP2 has different effects on normal cells and various types of cancer cells." (PMID 24191913, 2013). "IGFBP-2 is frequently overexpressed in advanced cancers and can be used for prediction of chemotherapy response and prognosis in some malignancy." (PMID 23165420, 2013). "The ability of IGFBP2 to support cancer cell survival or migration has been documented in other cancer cell types." (PMID 24191913, 2013). "In these analyses, both capture antibodies revealed a concordant and significant (p<0.05) difference in abundance of IGF1 (decreased in cancer) and IGFBP2 (increased in cancer), as shown in." (PMID 24282616, 2013). "At a cutoff value of 160.9 ng/ml, the specificity and sensitivity of using IGFBP2 alone to differentiate the cancer and healthy groups were 76.92% and 75.61%, respectively." (PMID 24069370, 2013). "In the same way, IGFBP-2 positively or negatively regulates cell growth and survival in certain types of cancers in both of in vitro and in vivo studies." (PMID 23165420, 2013). "In the same cell model, a neutralizing antibody to IGFBP-2 also inhibits cell growth and downregulates the expression of a number of potential cancer-promoting cytokines." (PMID 22927847, 2012). "Within this locus, we identified Igfbp5 and Igfbp2 as the best candidate cancer modifier genes, members of the insulin-like growth factor binding protein family." (PMID 22973541, 2012). "The capture assay found that the presence of antibodies to IGFBP-2 was significantly increased in the population of cancer patient samples, where 23% of patients were positive, compared to control samples, with a positive rate of only 1% (p = 0.008)." (PMID 18510754, 2008). "Western blotting of serum-free conditioned media from cells in culture showed that 8 out of 10 normal and 3 out of 10 cancer cultures produced a 32-kDa immunoreactive IGFBP-2." (PMID 9218734, 1997).
cancer (continued). "In the tissues, IGFBP-2 mRNA was expressed in all normal and cancer samples but other IGFBPs showed variable expression." (PMID 9218734, 1997). "Furthermore, IGFBP2 is capable of inducing excessive activation of its biological functions in cancer via multiple signaling pathways." (PMID 40728947, 2025). "IGFBP2 is a potential therapeutic target for cancer treatment." (PMID 38778379, 2024). "Circulating IGF-1 and IGFBP-2 are typically considered to be pro-tumorigenic; IGF-1 exhibits pro-proliferative and anti-apoptotic properties, while IGFBP-2 enhances cancer cell survival, proliferation, invasion, and migration, as well as intra-tumoral angiogenesis." (PMID 38928185, 2024). "Furthermore, in response to CM induction, eWATs secreted inflammatory adipokines associated with cancer metastasis, muscle atrophy, and vascularization (e.g., NGAL, CD54, IGFBP-2)." (PMID 37627795, 2023). "Conversely, high IGFBP-2 expression has been reported in the serum and tissues of several cancers." (PMID 38137390, 2023). "However, many studies consider only the intracellular IGFBP2 pool in cancer cells, where it appears to play a protumorigenic role." (PMID 37436978, 2023). "Notably, as expected, the COL1A1+/COL1A2+/IGFBP2+ fibroblast-like cells especially MSC-like-c2 present strong interactions with malignant tumor cells (MTC), which confirms our observation from in-house data." (PMID 37479733, 2023). "Additionally, the secretion of IL-10 can be upregulated by insulin-like growth factor binding protein 2 (IGFBP2) released from cancer cells following STAT3 activation." (PMID 37444617, 2023). "The addition of adipocytes into the coculture system also significantly reduced cancer cell proliferation, suggesting that adipocrine factors other than IGFBP2 may be able to exert additional anticancer effects." (PMID 37436978, 2023). "IGFBP2 is found to be highly expression in many of cancers, which may emerge as a potential prognostic indicator in various tumors." (PMID 35546443, 2022). "Both S100A4, a calcium-binding protein, and IGFBP2, an insulin-like growth factor-binding protein have roles in a multitude of cancer hallmarks including proliferation, angiogenesis, migration, invasion, and epithelial‐to‐mesenchymal transition, but their roles in CLL have not been characterized." (PMID 35301276, 2022). "Moreover, we carried out GSEA analysis to explore cancer and immune-related signaling pathways positively modulated by IGFBP2." (PMID 36110851, 2022). "Furthermore, the elevated IGFBP2 level had a poor outcome for OS according to cancer type, especially in GBM (HR = 1.36, 95% CI = 1.03–1.79), CRC (HR = 2.52, 95% CI = 1.43–4.44), and other cancers (HR = 2.09, 95% CI = 1.36–3.21)." (PMID 35546443, 2022). "IGFBP-2 has been characterized as exerting a unique influence on cancer metastasis, mediating the metastatic effect of miR-126 downregulation which has been observed in many cancers." (PMID 35597813, 2022). "Furthermore, cancer growth signaling moderated by the IGFBP2/IGF pathway has been extensively studied due to its mitogenic nature." (PMID 36142846, 2022). "But the potential mechanism of IGFBP2 in cancer is still vague." (PMID 35546443, 2022). "IGFBP-2 has been reported to involve in cancer metastasis, angiogenesis, and tumorigenesis." (PMID 34204873, 2021). "A study demonstrated that IGFBP2 can be located into the nucleus in several common cancer cells." (PMID 33498859, 2021). "Moreover, the nuclear IGFBP2 augments angiogenesis via increasing the promoter transcriptional activity of VEGF in cancer cells." (PMID 34066023, 2021). "In these cancer cells, IGFBP-2 acts as an oncogene, and the decrease in cell viability by AOFE treatment may be attributed to the possibility that the expression of IGFBP-2 may be regulated by AOFE treatment." (PMID 34728751, 2021).
cancer (continued). "Ionizing radiation stimulates EV release from GB cells, promoting a migratory phenotype in recipient cancer cells through the transfer of insulin-like growth factor binding protein 2 (IGFBP2) protein and connective tissue growth factor (CTGF) mRNA, thus aiding in radiotherapy resistance." (PMID 34210109, 2021). "It will be interesting to elucidate whether other cancer cell entities share IGFBP2 and MACC1 as pro-tumorigenic mediators for a common and synergistic consideration in future studies." (PMID 34830078, 2021). "IGFBP2 has been demonstrated to show promoted tumorigenicity in various cancer types." (PMID 32127912, 2020). "Our data may suggest that FOXA1 keeps IGFBP-2 in check in normal cells, but this negative regulation is lost in the cancer cells." (PMID 32655839, 2020). "Indeed, IGFBP2 exhibits a nuclear localization signal motif, responsible for its nuclear translocation, and, in cancer cells, nuclear IGFBP2 is involved in the transcriptional activation of the VEGF-A gene." (PMID 32302288, 2020). "However, the mechanisms by which IGFBP-2 contributes to the progression of cancer are still unclear." (PMID 32911852, 2020). "Additionally the IGFBP expressed at highest levels within ACC was IGFBP2, which has been recently suggested as a potential target for treatment in some type of cancers." (PMID 30838516, 2019). "IGFBP2 can participate in many different kinds of cancer as a potential biomarker." (PMID 30999686, 2019). "In addition to its functions as a secretory protein, IGFBP2 intracellular oncogenic functions promote cancer cell proliferation, invasion, metastasis and drug resistance." (PMID 30626422, 2019). "Measurement of circulating insulin‐like growth factors (IGFs), in particular IGF‐binding protein (IGFBP)‐2, at the time of diagnosis, is independently prognostic in many cancers, but its clinical performance against other routinely determined prognosticators has not been examined." (PMID 29722920, 2018). "Overexpression of IGFBP2 and IGFBP5 have been associated with poorer cancer prognosis." (PMID 29758070, 2018). "IGFBP-2 has been demonstrated to be an enhancer of IGF-1 function in several types of cancer." (PMID 28903396, 2017). "These collective observations strongly suggest that IGFBP2 may be involved in the development and progression of malignant tumors in general." (PMID 28036255, 2017). "In general, IGFBP2 is related to oncogenesis and its expression is often elevated in cancer." (PMID 27901484, 2017). "IGFBP-2 is the dark horse in metabolism and cancer, and it is once again in the spotlight." (PMID 28977895, 2017). "The physiologic roles of IGFBP2 in cancer are under active investigation." (PMID 28036255, 2017). "Furthermore, a microarray analysis of PRAME shRNA-silenced leukemic cells revealed that PRAME alters the expression of two additional genes, IL-8 and IGFBP2, that are potentially involved in carcinogenesis and cancer progression." (PMID 28903396, 2017). "This suggests that a novel potential mechanism of the anti-cancer effects of metformin may be by the regulation of IGFBP-2." (PMID 27754854, 2017). "The correlation between cancer and IGFBP2 has seldom been mentioned previously." (PMID 28903396, 2017). "In high-grade pre-malignant cervical lesions infected with HPV16 the IGFBP2 levels are reduced, suggesting that changes in insulin signaling may play a key role cancer progression." (PMID 27537218, 2016). "There is abundant evidence that IGFBP2 plays a role in promotion of various cancers." (PMID 27579675, 2016). "Loss of MIR-491 could regulate IGFBP2, CDK6 and EGFR proliferative pathways, by which the propagation of GBM cancer stem cells was inhibited." (PMID 27905892, 2016). "In order to better understand whether regulation of IGFBP2 expression is de-regulated in cancer, it will be important to further establish how it is regulated in the physiological setting." (PMID 25774149, 2015).
cancer (continued). "Protease cleavage of IGFBP2 could be partially responsible for the lack of association, and also help to explain the differential findings of IGFBP2’s role in cancer." (PMID 25774149, 2015). "For example, there are numerous reports indicating the involvement of IGFBP2 in proliferation, migration and invasion of cancer cells, and elevated levels of IGFBP2 have also been reported in the serum and plasma of CRC patients when compared to normal controls." (PMID 25793510, 2015). "Furthermore, the MCF7 cell line is known to secrete low levels of full-length IGFBP2 compared to other cancer cell lines even though the mRNA and intracellular protein levels of IGFBP2 are comparable, suggesting high levels of proteolytic degradation." (PMID 25774149, 2015). "The inferior prognosis of CRC patients expressing low IGFBP3 or high levels of IGFBP2 suggests that IGFBPs are also implicated in CRC tumorigenesis, either operating as negative regulators of IGFs activity or exerting IGF-independent effects on cancer growth." (PMID 26528439, 2015). "Compensatory pathways may also influence cancer growth, and the computational results presented here warrant targeted experimental testing focusing on the IGFBP2-HIF1α interaction in the context of other signaling networks." (PMID 25884993, 2015). "The role of insulin-like growth factor binding protein 2 (IGFBP2) in cancer is unclear." (PMID 25774149, 2015). "There are multiple factors, which can influence IGFBP2 expression and which can alter our interpretation of these findings; in the following sections, we propose that future experiments should aim to account for these factors in order to improve our understanding of IGFBP2’s role in cancer." (PMID 25774149, 2015). "Through detailing factors, which influence IGFBP2 expression alongside measurements in patient samples our current understanding of its role in cancer could be improved." (PMID 25774149, 2015). "This difference may be due to the fact that rapidly dividing cancer cells are more sensitive to chemotherapy and/or modulation but also that IGFBP2 may affect different pathways depending on the presence or absence of additional growth factors." (PMID 26317790, 2015). "Despite this extensive investigation, IGFBP2 has not yet been implemented as a cancer biomarker due to contradictory findings as to whether IGFBP2 is up- or down-regulated in different cancers." (PMID 25774149, 2015). "In addition, also single supplementations, e.g., lycopene in humans, or vitamin D analogs in cancer cell lines can induce or repress IGFBP-2 concentrations." (PMID 24778626, 2014). "Together, those results suggest that IGFBP2 could be a common oncogenic protein for various types of cancers." (PMID 24069370, 2013). "The role of IGF binding protein 2 (IGFBP2) in cancer development is intriguing." (PMID 24191913, 2013). "The role of IGFBP2 in cell growth and cancer development is intriguing." (PMID 24191913, 2013). "Interestingly, population-based association studies in humans detected a significant association between cancer risk and SNPs mapping in a 50-kb interval encompassing the IGFBP5 and IGFBP2 genes." (PMID 22973541, 2012). "Within this locus, Igfbp5 and Igfbp2 are good candidates for cancer modifier of lung tumorigenesis." (PMID 22973541, 2012). "However, studies have also shown that Igfbp2 is overexpressed in a wide spectrum of cancers and IGF-independent effects of Igfbp2 are emerging." (PMID 20808936, 2010). "Integrins have been previously found to interact with IGFBP2 in cancer cells." (PMID 20573191, 2010). "Furthermore, significantly greater levels of IGFBP-2 antibody immunity were found in cancer patients compared to normal controls (p = 0.008)." (PMID 18510754, 2008).
cancer (continued). "Based on these studies, we speculate that the combination of ICA and CUR directly targets the DNMT1/IGFBP2 axis to affect cancer cell development and the level of PD-L1 to influence the differentiation of immune T cells, thereby affecting cancer cell development." (PMID 38778379, 2024). "Additionally, IGFBP-2 is upregulated in several cancers and promotes several pathways involved in oncogenic signaling, including the stimulation of proliferation, epithelial–mesenchymal transition, invasion, metastasis, and angiogenesis, all of which are independent of IGF-1." (PMID 38137390, 2023). "It has also been suggested that IGFBP2 may play a role in immune evasion by tumors, as it can suppress the activity of natural killer cells, which are important for immune surveillance against cancer cells." (PMID 37928523, 2023). "Elevated circulating IGFBP-2 levels have also been linked to non-survival in cancer patients." (PMID 38137505, 2023). "Moreover, a variety of cellular processes, such as cellular migration, invasion, angiogenesis, epithelial‐to‐mesenchymal transition(EMT), and transcriptional activation, are related to high IGFBP2 expression in many cancers, thus participating in the development of various cancers." (PMID 35546443, 2022). "Thus, there is an urgent need of a focused meta‐analysis of the role of IGFBP2 in cancer prognosis." (PMID 35546443, 2022). "Thus, IGFBP2 may serve as a great biomarker of prognosis in various cancers, and it is worthy of further study to add it to the established risk prediction model to provide clinical the basis for individualized treatment plan." (PMID 35546443, 2022). "However, mean IGFBP2 SDS were significantly higher in the cancer population compared to controls." (PMID 26528439, 2015). "Importantly, IGFBP-2 is frequently overexpressed in advanced cancers, suggesting that it may be involved in the metastatic process." (PMID 23165420, 2013). "Furthermore, it has been seen that IGFBP-2 may regulate the expression of several potential cancer-promoting cytokines including fibroblast growth factors 6 and 7 (FGF-6 and -7), neurotrophin-4 (NT-4), and placental growth factor (PIGF)." (PMID 22927847, 2012). "Moreover, IGFBP-2 is a highly sensitive marker of malignant progression in different tumors and potentially involved in anti-apoptosis, angiogenesis, and metastasis during cancer progression." (PMID 19521519, 2009). "Blockage of IGFBP2 may thus constitute a viable strategy for targeted cancer therapy." (PMID 15686601, 2005). "Third, multiple studies have reported that proteins such as transcription factor IIB-related factor 2 (BrF2), insulin-like growth factor-binding protein 2 (IGFBP-2), and CD151 play regulatory roles in cancer cell growth, proliferation, migration, and invasion." (PMID 41156537, 2025). "IGFBP2 specifically can bind to insulin, IGF-1, and IGF-2 but binds with the highest affinity to IGF-2; however, it plays multiple roles in cancer in an IGF-independent manner." (PMID 39007351, 2024). "IGFBP2 occupies a pivotal position within the IGFBP family and exerts significant oncogenic effects in diverse types of human cancers." (PMID 38778379, 2024). "Cumulatively, we see that IGF-II depletion phenocopies IGFBP2 anti-invasive action in the TNBC and DCIS.com cell lines, supporting a model of stromal IGFBP2 disrupting proinvasive IGF-II autocrine signaling in cancer cells." (PMID 37436978, 2023). "Having established the biological activity of the clover-tagged IGFBP2, we next applied the concentrated IGFBP2 medium (from the TIFs) to MM231 cells and assessed IGFBP2 binding to cancer cells using flow cytometry." (PMID 37436978, 2023).